YY1 (YY1 transcription factor)
Diseases named in the same sentence as YY1 in open-access papers (continued):
Sharing a sentence is not in itself a finding about the gene and the disease.
cancer (continued). "YY1 triggers the development of deadly cancer phenotypes with enriched presence of highly tumorigenic cells in the tumors, suggesting that YY1 may regulate the CSC phenotype." (PMID 33728560, 2021). "Analogous to its role in healthy state, YY1 has a highly context-dependent function also in cancer." (PMID 33102493, 2020). "YY1 has been reported to be overexpressed in multiple cancers, including HCC." (PMID 32272940, 2020). "YY1 can function as transcription factor and plays an important regulatory role in various biological processes by binding to DNA and numerous proteins, consequently impacting the pathologic processes of cancers." (PMID 32272940, 2020). "This may be explained by a cancer cell-type specific role of YY1, HSF1 and SP1 in regulating basal Ub gene expression." (PMID 32751694, 2020). "An alternative explanation could be the presence of mutated transcription factors’ binding sites along the BIRC5 promoter in cancer cells, which might affect the overall binding of the various transcriptional regulators, including YY1." (PMID 32899428, 2020). "Moreover, the effect of modulating YY1 expression levels on Raji cellular growth, as well as on cellular viability following anti-cancer treatments was evaluated, confirming the pro-tumorigenic role of both YY1 and survivin in these cells." (PMID 32899428, 2020). "In cancer, the pleiotropic YY1 transcription factor plays a controversial role." (PMID 32899428, 2020). "In addition, BPTF, SIN3A, CNOT1 and YY1 were highly positively correlated in both pan-cancer and ccRCC datasets." (PMID 33232269, 2020). "Moreover, several studies have demonstrated that YY1 is involved in cisplatin responsiveness, in different cancer models." (PMID 32806777, 2020). "It is important to note that YY1 binds the BIRC5 promoter in both cancer and normal cell lines." (PMID 32899428, 2020). "Therefore, novel tools for dissecting the dynamics of YY1/YY2 should be developed and used to direct the targeting of YY1, eventually leading to a significant addition to currently available cancer treatment regimens." (PMID 32226547, 2020). "Furthermore, recent studies also have demonstrated the important role of YY1-related non-coding RNAs in acquiring cancer-specific characteristics." (PMID 32226547, 2020). "Therefore, we performed a functional knockdown screen of 92 cancer associated transcription factors and identified GATA3, SPDEF, IRF9, and YY1 as candidate transcriptional activators/repressors for APOBEC3B gene expression." (PMID 32934779, 2020). "Whether YY1 is overexpressed in a wide-range of cancers, and whether YY1-mediated enhancer–promoter interactions are universal features in cancer cells needs further investigation." (PMID 32941624, 2020). "Therefore, the findings of the present study are consistent with the previous reports and further corroborate the role of YY1 in modulating genes relevant in the context of cancer progression." (PMID 31217904, 2019). "The authors further demonstrated that miR-192-5p mediated cancer behaviours by targeting YY1." (PMID 31873114, 2019). "In this section, we discuss the role of YY1 in different cancers in detail." (PMID 31824839, 2019). "YY1 Protein-protein interactions and their role in cancer progression/suppression." (PMID 31824839, 2019). "YY1 reported inhibitors and their inhibition mechanism in different cancers." (PMID 31824839, 2019). "Several recent reports have indicated targeting YY1 by various drugs in different cancer models." (PMID 31824839, 2019). "YY1 has been shown to be over expressed and promote cancer in hematological malignancies." (PMID 31824839, 2019). "YY1 is known to integrate several bio-molecular pathways in cell; therefore its role in patho-physiological manifestation of different human diseases, especially in cancer, has been extensively studied." (PMID 31217904, 2019). "Therefore, we believe that the p300/YY1/miR-500a-5p/HDAC2 signalling axis plays important roles in cancer development." (PMID 30737378, 2019).
cancer (continued). "Hence, a collection of YY1-protein interactions in the context of different cancers would help us gain an insight into how YY1 promotes or suppresses cancers." (PMID 31824839, 2019). "Yin-Yang 1 (YY1) is a key transcription factor involved in cancer progression." (PMID 31799179, 2019). "Moreover, immuno-histochemical of analysis of cancer tissue microarrays revealed that YY1 levels were highly expressed in papillary thyroid cancer (PTC) compared to follicular thyroid cancer (FTC)." (PMID 31824839, 2019). "The overexpression of YY1 in the majority of cancers has been correlated with poor prognosis." (PMID 31703732, 2019). "Eventually, YY1 regulates specific tissue genes that are important for the response to therapy in each type of cancer; but we cannot ignore the fact of the high stability of YY1 protein and the relative independence of the protein levels from transcript levels in B-NHL cell lines." (PMID 29564133, 2018). "YY1 also directly interacts with several important cancer-related regulators including AKT23." (PMID 29970878, 2018). "There is increasing evidence that YY1 is important in cancer development." (PMID 28412749, 2017). "In addition to regulating protein-coding genes, YY1 can also modulate the expression of noncoding genes, such as microRNAs (miRNAs) present in human cancer cells." (PMID 29052509, 2017). "YY1 is a key transcription factor and plays different roles in various cancers." (PMID 28485541, 2017). "YY1 is a DNA-binding transcription factor and reported to be involved in cancer progression." (PMID 28489564, 2017). "Similarly, YY1 has multiple critical roles in various biological processes, ranging from cell proliferation to cell differentiation, and from cancer progression to embryogenesis." (PMID 28412749, 2017). "Yin-Yang 1 (YY1) has been reported to be involved in autophagy in several carcinomas." (PMID 29052509, 2017). "Patterns of YY1 protein expression levels in human cancers have been reviewed previously." (PMID 27225481, 2016). "Moreover, after we artificially over-expressed YY1 protein, the cancer cells became more sensitive to drugs." (PMID 25885449, 2015). "Most cancers show increased expression of YY1 while a few show a lowered expression." (PMID 25053986, 2014). "A few reviews on YY1 have been published that cover some of the roles of YY1 in normal and cancer." (PMID 25053986, 2014). "Therefore, an immediately appealing follow-up study from our current analysis would be to experimentally validate the interaction between the two key expression regulators hsa-miR-548p and YY1 in AML patient samples or cancer cell-lines such as K562." (PMID 25340776, 2014). "However, the data are somewhat diverse, with some cancers showing increased YY1 expression and some showing decreased expression." (PMID 24884523, 2014). "Elevated YY1 levels in these cancers may decrease PSCA levels by direct binding of YY1 to the inhibitory site in the promoter." (PMID 22536409, 2012). "YY1 itself has been classified as an oncogene and was found to be upregulated in many cancer types." (PMID 21253604, 2011). "YY1 over-expression has been reported to affect the clinical behavior of several cancer types." (PMID 21483740, 2011). "High levels of YY1 may be advantageous to transformed cells during the early stages of cancer development, principally by reducing the tendency toward apoptosis." (PMID 19566924, 2009). "On the other hand, the unusually high levels of YY1 protein observed in cancer cells might be an outcome of mis-regulated YY1 transcription." (PMID 19712462, 2009). "By demonstrating how YY1 maintains prognostic value in a distinct population, we contribute valuable insights validating YY1 as a biomarker and emphasize the relevance of incorporating advanced pathology tools such as TMAs and DP into future translational cancer research." (PMID 41009346, 2025).
cancer (continued). "Furthermore, YY1 functions in cancer cell stemness and prognosis for PRAD." (PMID 40344383, 2025). "Additionally, gene ontology analysis indicated that CBSs may be involved in diverse biological processes beyond cancer, including axon development and synaptic organization, consistent with the broad expression patterns of both YY1 and TFAP2." (PMID 40953061, 2025). "Of note, the double knockdown of YY1 and MYC consistently showed low cancer scores after perturbations in the majority of cases, confirming that the combination of YY1 and MYC may exhibit synergistic effects, rendering them promising target genes for cancer reversion." (PMID 39840939, 2025). "In addition to YY1′s role in upregulating inhibitory receptors on T cells, it also intrinsically regulates the anti-apoptotic mechanisms in cancer cells by primarily overexpressing several anti-apoptotic gene products and repressing immune receptors on CD8 T cells, such as Fas and DR5." (PMID 39796650, 2024). "Therefore, further research on the synergistic effects of YY1 blockers along with the PD-L1 blocker pentamidine could shed light on a more robust immune attack against cancer cells." (PMID 38539569, 2024). "Moreover, YY1 is characterized by its dual nature in cancer, whereby it may be involved in either the promotion or suppression of tumorigenesis." (PMID 38893192, 2024). "Therefore, YY1 has the ability to promote oncogenic proliferation in cancer cells." (PMID 37686541, 2023). "Besides, YY1 has been considered to be an inducer of cancer metastasis." (PMID 36195720, 2023). "However, the role of YY1 in tumorigenesis remains controversial and its regulatory effects may depend upon not only cancer types, but also its interacting partners, chromatin structure, and the context in which it acts." (PMID 36880159, 2023). "Moreover, overexpression of YY1 has been observed in various types of cancer." (PMID 37928273, 2023). "Therefore, YY1 is a critical target for immunotherapy and chemotherapy of cancers." (PMID 37081988, 2023). "Moreover, YY1 is considered a master regulator in various stages of embryogenesis, especially in neural crest stem cells (NCSCs) survival and proliferation as it acts as transcriptional repressor on cancer stem cells-related transcription factors." (PMID 35719931, 2022). "In addition to this indirect regulatory loop, it has also been observed that YY1 might directly inhibit the expression of RKIP in several cellular cancer models, as also supported by some unpublished observations." (PMID 35205667, 2022). "In addition, YY1 can also stay in both the nucleus and cytoplasm, especially in cancer cells." (PMID 35406384, 2022). "Therefore, YY1 has different roles in various cancers, and its role in PDAC is still unclear." (PMID 36123703, 2022). "In addition, YY1 dimerization or oligomerization may be important for cell differentiation and embryonic development but indispensable for the proliferation of cancer cells, which are already in a chaotic state of gene expression." (PMID 35406384, 2022). "Accordingly, JAC1 may exert anti-cancer effects in YY1-overexpressed malignant tumors." (PMID 36230577, 2022). "Furthermore, YY1 is involved in multiple molecular mechanisms, enhancing all hallmarks of cancer." (PMID 33728560, 2021). "Furthermore, the transcription factor Yin-Yang 1 (YY1) is known to further enhance the effects of PD-L1; therefore.NO-mediated inhibition of YY1 and subsequent downregulation of PD-L1 further enhances the immune response in cancer." (PMID 34685635, 2021). "YY1 may thus be a key signaling molecule mediating cancer progression." (PMID 33985581, 2021). "Additionally, high expression levels of both YY1 and Sox2 were common in specific types of cancer." (PMID 33728560, 2021). "However, whether USP21/YY1/SNHG16 plays a cancer-promoting role in a feedback loop needs to be further studied." (PMID 31956270, 2020).
cancer (continued). "Moreover, it has been reported that YY1 has a high expression level in many types of cancer, such as gastric cancer and prostate cancer, and it promotes cancer cell proliferation and metastasis, thus acting as an oncogene in cancer development." (PMID 31956270, 2020). "Therefore, a better comprehension of the YY1-mediated molecular mechanisms that are activated or inhibited in the different kind of cancers may help in the development of novel diagnostics, as well as effective therapeutic strategies." (PMID 32899428, 2020). "In addition, the computational analysis performed on several B-NHLs Gene Expression Omnibus (GEO) curated gene expression datasets gave new insights on the significantly correlated upregulation of both YY1 and survivin in cancer patients compared to normal subjects." (PMID 32899428, 2020). "Hence, a detailed picture of YY1 interacting partners from different cancer models would help us understand the biology of YY1 in cancer to a greater detail, which would eventually help us develop novel therapeutic strategies for cancer cure that are centered around targeting YY1." (PMID 31824839, 2019). "Additionally, we discuss the reported YY1 inhibitors and their role in cancer therapeutics." (PMID 31824839, 2019). "Therefore, better understanding of YY1 protein structure, function, and its altered protein-protein interactions (PPIs) in various cancers would not only help understand the role of YY1 in cancer but also in the design and development of novel therapeutic strategies." (PMID 31824839, 2019). "Involvement of YY1 in the regulation of genes that are directly linked to malignant transformation indicated that YY1 might play a key role in many cancers, and indeed YY1 has been reported to be highly expressed in many cancers and is essential for cancer progression." (PMID 31824839, 2019). "Moreover, overexpression of YY1 confers cancer cells with resistance in chemotherapies." (PMID 29970878, 2018). "Why YY1′s correlation with clinical outcomes is inconsistent among different cancers is unknown." (PMID 28412749, 2017). "In the past few years, the transcription factor Yin-Yang 1 (YY1), which is ubiquitously expressed and highly conserved, has been reported to regulate expressions of downstream genes to affect the sensitivity and resistance of cancer cells to chemotherapeutic drugs." (PMID 28489564, 2017). "YY1 could be involved in the sensitivity and resistance of cancer cells to chemotherapeutic drugs." (PMID 28489564, 2017). "Therefore, it will be valuable to investigate whether YY1 methylation is enriched and therefore serves as a biomarker in cancers." (PMID 26902152, 2016). "Thus, the enrichment of cells expressing high levels of YY1 in the LT-HSC cell population argue that YY1 might be involved in cancer stem cell function and therefore could be a potential therapeutic target for some hematopoietic malignancies." (PMID 22292011, 2012). "YY1 may play a role at several different points in cancer development and progression." (PMID 19566924, 2009). "The transcription factor Yin Yang 1 (YY1) and the Raf kinase inhibitory protein (RKIP) represent two molecular entities with diametrically opposed roles in cancer biology." (PMID 41327312, 2025). "Further, the expression of YY1 was significantly positively correlated with the expression of METTL3 in clinical cervical and breast cancer patients from TCGA." (PMID 39800682, 2025). "Our findings reveal a new transcriptional network between YY1 and TFAP2 that influences HPV-driven cancer." (PMID 40953061, 2025). "Therefore, targeting the YY1/DR5 axis may be an effective anti-cancer strategy." (PMID 40422804, 2025). "Another publication demonstrated that YY1 activates DCUN1D5 acting on the PI3K/AKT pathway, which stimulates cancer progression in TNBC patients." (PMID 41009346, 2025).
cancer (continued). "Mechanistically, Notch1 overexpression upregulates the expression of transcriptional factor YY1 (Yin-Yang 1), which in turn represses ICAM1 expression to prohibit CD8+ T cell-derived granzyme-driven cancer cell pyroptosis and cytotoxicity." (PMID 41271562, 2025). "Our analysis revealed MYC and YY1 as key elements of double‐negative feedback loops which interconnect core regulatory circuits associated with normal and cancer attractors, indicating that these TFs can potentially act as master regulators for cancer reversion." (PMID 39840939, 2025). "This study aims to identify additional host proteins binding to the lnc-FANCI-2 promoter through proteomic analysis and proposes a model for how TFAP2 and YY1 regulate lnc-FANCI-2 and other cancer-related genes in both primary and cancer cells." (PMID 40953061, 2025). "Through this suppression of YY1, RKIP can alleviate chemoresistance and immune-resistance in cancer cells, thereby sensitizing them to death receptor-mediated apoptosis." (PMID 41459495, 2025). "The proposed dysregulated resistant circuit involving NF-κB, YY1, Mcl-1, and DR5, modified by Obatoclax, offers insights into potential therapeutic strategies for overcoming resistance in GBM cancer cells." (PMID 38893192, 2024). "We also used ImmuCellAI to explore the correlation between YY1, CD274, and LAG-3 expression and immune infiltration in various cancers." (PMID 39796650, 2024). "Our findings collectively suggest that YY1 transcriptionally upregulates IL32 secretion from pericytes, influencing their paracrine effect on TKI sensitivity in cancer cells." (PMID 39435643, 2024). "Recent studies also reveal that inhibiting HnRNP L decreases PD‐L1 expression and enhances antitumor immunity by destabilising YY1 mRNA in castration‐resistant prostate cancer (CRPC), thereby promoting T cell‐mediated cancer cell ferroptosis." (PMID 38594879, 2024). "Mechanistically, YY1 transcriptionally up‐regulates IL32 secretion from PCs, which then activates the β5‐integrin‐Src‐Akt signaling pathway in EGFR‐mutant cancer cells to confer their TKI sensitivity." (PMID 39435643, 2024). "To determine the regulatory role of YY1 in PC‐mediated cancer cell sensitivity to TKI drugs, we performed co‐culture experiments with siYY1/siNSC‐transfected PCs and cancer cells." (PMID 39435643, 2024). "YY1 was identified as a regulator of IL32 expression in PCs, and YY1 silencing countered the inhibitory effect of PCs on cancer cell TKI sensitivity." (PMID 39435643, 2024). "This study shows that KDM5C binds to YY1, that it facilitates YY1 chromatin recruitment, and that targeting YY1 increases the vulnerability of KDM5C-low cancer cells." (PMID 39433896, 2024). "YY1 was shown to bind SEs driving QKI, RAE1, FOXC1, and MET1 transcription in HCC, HGSOC, and TNBC, respectively, which positively affects cancer-cell migration and invasion (Table A1)." (PMID 38542080, 2024). "In summary, our work demonstrates a synthetic lethal interaction between YY1 and KDM5C and suggests combination therapies for cancer treatments." (PMID 39433896, 2024). "We also provide evidence for a possible role of YY1, GATA1, and C/EBPα in MGP transcription regulation in human cancers." (PMID 39684309, 2024). "YY1 mRNA expression also had an inhibitory effect on the EMT (12%), hormone ER (12%), RASMAPK (19%), and RTK (12%) pathways, pan-cancer." (PMID 37894300, 2023). "Dysregulation of YY1 and PEBP1 expression patterns has been reported across different types of cancer." (PMID 37894300, 2023). "Here, we found various correlations between YY1/PEBP1 expression (or methylation) and genomic alterations, such as SNVs and CNVs that exhibited a cancer type-specific pattern." (PMID 37894300, 2023). "Researchers have elucidated the complex regulatory relationship between EPAS1 and PI3K/AKT signaling pathway in different cancers, in which factors such as PTEN, YY1, SCD1, and CD44 also play important roles." (PMID 37124944, 2023).